CDKN2A (cyclin dependent kinase inhibitor 2A)
Diseases named in the same sentence as CDKN2A in open-access papers (continued):
Sharing a sentence is not in itself a finding about the gene and the disease.
glioma (continued). "Thereby, our study provides a cost effective and convenient method for evaluating CDKN2A homozygous loss status in glioma, as an alternative to expensive genomic sequencing." (PMID 37138345, 2023). "Given that CDKN2A encodes tumor suppressors and the current literature correlates only homozygous CDKN2A loss with prognosis and grade in gliomas and meningiomas, determining hemizygous loss in our cohort was deemed irrelevant." (PMID 37138345, 2023). "Comparison of low-grade gliomas with progression to higher-grade counterparts, with loss of chromosome 9 and the CDKN2A locus found to be significantly associated with tumour progression." (PMID 37504251, 2023). "The 2341 cell line of BRAFV600E-mutated and CDKN2A-deleted glioma injected into both immunodeficient (NSG) and immunocompetent (FVB/N) mice have revealed successful engraftment and has been critical for the preclinical assessment of experimental therapeutics." (PMID 37920169, 2023). "High-grade gliomas display decreased CDKN2A expression levels, whereas CDKN2A mutations were observed in the recurrent meningiomas." (PMID 34854470, 2022). "Taken together, the integrity of CDKN2A/B distinguishes the biological outcomes of IDH mutation during the course of glioma progression, in accordance with its impact on patient survival." (PMID 35203456, 2022). "We identified the main negative prognostic factors that support the aggressiveness of grade 4 gliomas: patient comorbidities, type of surgical resection, degree of cell differentiation, and CDKN2A gene mutations." (PMID 36136867, 2022). "Other molecular mutations frequently reported in gliomas, including chromosome 9p deletion and subsequent CDKN2A gene loss, have also been postulated to be involved in oligodendroglioma pathogenesis and malignant progression." (PMID 35957904, 2022). "The detection and reporting of alterations such as IDH1/2 mutation, 1p/19q co-deletion, EGFR amplification, TERT-promoter mutation, and CDKN2A homozygous loss in the diagnosis of infiltrating glioma has become standard practice in clinical neuropathology." (PMID 36397144, 2022). "For IDH mutant histologically lower-grade gliomas, the molecular diagnostic criterion for glioblastoma is the homozygous deletion of CDKN2A/B." (PMID 35558510, 2022). "The prognosis-related independent risk factors FDX1 and CDKN2A identified from CARSs are considered potential prognostic biomarkers for WHO 2/3 glioma." (PMID 36059638, 2022). "Homozygous deletion of the CDKN2A locus is associated with a poor prognosis and is associated with progression to high-grade gliomas." (PMID 36147920, 2022). "FISH examination of the CDKN2A gene revealed mutations, such as deletion or amplification in 31.25% of cases, exclusively among grade 2 gliomas." (PMID 36290853, 2022). "Although hotspot mutations in isocitrate dehydrogenase (IDH) genes are associated with favorable clinical outcomes in glioma, CDKN2A/B homozygous deletion has been identified as an independent predicator of poor prognosis." (PMID 35203456, 2022). "Across brain tumor subtypes, such as glioblastoma and low-grade glioma, differences in mutation rates showed the same trend in eight driver events among C1/2 subtypes, including CDKN2A/CDKN2B and PTEN deletion, IDH mutation, and co-deletion of 1p and 19q." (PMID 34722280, 2021).
glioma (continued). "CDKN2A homozygous deletion is also observed in pediatric gliomas, and is a well-known hallmark lesion of pleomorphic xanthoastrocytoma." (PMID 33673070, 2021). "Allelic loss of 9p21.3, which contains CDKN2A, is a prognostic factor in 1p/19q-codeleted grade 3 gliomas." (PMID 34638714, 2021). "Of further relevance to the dLGG IDH-mut gliomas is the homozygous deletion of cyclin-dependent kinase inhibitor 2A/B (CDKN2A/B) that is associated with markedly shorter overall survival in IDH-mut tumors." (PMID 35083156, 2021). "Previous reports suggest that BrafV600E expression in neural progenitors is not sufficient for tumorigenesis and needs to cooperate with Ink4a or Cdkn2a locus deficiency in oligodendrocyte or astrocyte precursor cells to induce glioma formation." (PMID 33863883, 2021). "Among cancer gene deletions, CDKN2A loss defined multiple subgroups associated with poor survival including papillary kidney cancer (c1), low-grade glioma (c4), lung adenocarcinoma (c4), and soft tissue sarcoma (c1)." (PMID 33272320, 2020). "For instance, the integrative analysis of the glioma using survClust revealed a small novel subtype characterized by CDKN2A deletion and IDH1/2 mutation, whereas the individual platform analysis mostly agreed with previously known subtypes." (PMID 33272320, 2020). "Within the infantile cohort, there were no significant mutations and copy number changes beyond the NTRK fusion; the exception was case 3, a high-grade glioma with histology most consistent with anaplastic PXA that showed CDKN2A/2B loss." (PMID 32665022, 2020). "In our series, high histological grade and CDKN2A homozygous deletion were adverse prognostic factors in IDH-mutated-1p/19q intact gliomas." (PMID 33228806, 2020). "Rather, it harbors a BRAF V600E mutation and focal CDKN2A/B deletion, classifying this model as a high-grade glioma, herein denoted as an astrocytoma." (PMID 31693904, 2019). "In contrast, when an Egfr activating mutation was introduced in the presence of Cdkn2a loss, gliomas arose at a high frequency particularly on the nestin-TVA (Ntv) background." (PMID 31505839, 2019). "Factor 41 is associated with CDKN2A/B and with mesothelioma, kidney, and glioma, where the loss of CDKN2A/B is common." (PMID 31695042, 2019). "The authors concluded that Egfr activating mutations alone are insufficient to generate gliomas but can cooperate with predisposing mutations such as those of Cdkn2a to produce these tumours." (PMID 31505839, 2019). "Mutations in cancer driver genes such asTP53,CDKN2A, andEGFR, which are frequently affected in gliomas, have been shown to be rare in ependymomas." (PMID 32612806, 2019). "A related study into the cellular origin of gliomas investigated the role of Egfr (activation) and Cdkn2a (loss) mutations in various brain cell types." (PMID 31505839, 2019). "In LGG, the ceRNAs shared by MTAP and CDKN2A contained many genes highly associated with gliomas and other cancers, such as IDH1 and CDK4/6." (PMID 31719831, 2019). "For example, VOPP1 and CDKN2A, which have been proved important in glioma, were linked by KCTD5 in GBM." (PMID 31719831, 2019). "Pleomorphic xanthoastrocytoma is a circumscribed glial neoplasm that is genetically characterized by concurrent CDKN2A homozygous deletion and BRAF p.V600E mutation (or less commonly BRAF or RAF1 fusion)." (PMID 29880043, 2018). "In order to further understand the interplay between BRAF V600E mutation and the chromosomal region abrogating the CDKN2A gene: 9p21, a cohort of 100 pediatric gliomas was retrospectively analyzed." (PMID 30558563, 2018).
glioma (continued). "A large proportion of gliomas have a dysfunctional CDKN2A, the gene encoding the cyclin D1 inhibitor p16INK4A." (PMID 28074274, 2017). "Here, we present results from the characterization and therapeutic testing of a newly developed BrafV600E-expressing Cdkn2a deficient glioma model, the first to involve the use of BrafV600E glioma cells in a syngeneic, immunocompetent host." (PMID 27713119, 2016). "Results from the use of BrafV600EInk4a-Arf knock-out murine allografts and BRAFV600E + CDKN2A-deficient human glioma xenografts demonstrated the anti-tumor activity of PLX4720, a tool compound of the FDA-approved BRAFV600E-inhibitor vemurafenib." (PMID 27713119, 2016). "Although, association with tumor grade was not analyzed in our study due to the small number of low grade glioma, we found two risk variants in the CDKN2A and CDKN2B regions associated with mutated IDH1." (PMID 26839018, 2016). "Recent data of The Cancer Genome Atlas (TCGA) consortium on lower grade (WHO grade II and III) gliomas show that IDH mutations in these gliomas are virtually mutually exclusive with homozygous deletion of CDKN2A and with amplification of EGFR." (PMID 25943885, 2015). "Recurrent alterations in EGFR amplified gliomas were both focal, such as CDKN2A homozygous deletions, and large, such as chromosome 10 loss." (PMID 26257825, 2015). "The CDKN2A tumor suppressor genes appear to contribute to glioma predisposition, both from common single nucleotide polymorphisms and from rare mutations." (PMID 25563358, 2014). "We reported that expression of CDKN2A (encoding p16 protien) was lower in the patients with high-grade malignant glioma than low-grade glioma." (PMID 21843312, 2011). "Cyclin D1 overexpression, CDKN2A loss, and pRb inactivation play a key role in glioma tumorigenesis." (PMID 21843312, 2011). "Five of the genes, TERT, SLC6A18, CLPTM1L, and CDKN2A/B, have previously been shown to be associated with glioma by other GWA studies." (PMID 21827660, 2011). "It was reported that CDKN2A be mutated and deleted in various human tumors, including more than 70% of human glioma cell lines and glioblastoma." (PMID 21843312, 2011). "In this study, we identify that expression of CDKN2A was associated with grade of glioma in 61 patients with malignant glioma and glioma cells." (PMID 21843312, 2011). "Loss of CDKN2A/B confers with aggressive biological behavior and poor prognosis in gliomas." (PMID 41438586, 2026). "According to preclinical data, CDKN2A deficiency sensitizes IDH-mutant glioma to CDK4/6 inhibitors." (PMID 41546701, 2026). "This is presumably fostered by inactivation of CDKN2A, which is frequently mutated in gliomas." (PMID 41350483, 2025). "This study sought to explore the prevalence of BRAF V600E mutation and CDKN2A deletion in pediatric patients with high-grade glioma (HGG) and aimed to add to the scarce data in the literature about the prognosis of this subset of patients treated with traditional surgery, radiation and chemotherapy." (PMID 40860828, 2025). "The 2021 WHO Classification of Central Nervous System Tumors achieves refined risk stratification by elevating the prognostic weight of molecular markers (e.g., CDKN2A/B homozygous deletion directly defining grading) and incorporating novel molecularly defined tumor entities." (PMID 41377022, 2025). "In addition, this study suggests that CDKN2A homozygous deletion should be stronger than IDH mutation in the prognosis of CNS WHO grade 4 glioma patients." (PMID 39457569, 2024). "However, recent studies have shown that CDKN2A/B loss points towards a more aggressive phenotype, even when derived from low-grade gliomas." (PMID 39457569, 2024).
glioma (continued). "Furthermore, in histologically lower-grade adult gliomas, CDKN2A homozygous deletion is associated with a more aggressive clinical course and is a molecular marker of Grade 4 status in the latest WHO classification." (PMID 39108689, 2024). "It was reported that development of a high-grade glioma phenotype was associated with temozolomide-driven hypermutation and acquired alterations of the cell cycle regulators CDKN2A and CCND2, which have been shown to occur exclusively in post-radiation IDH—mutant gliomas." (PMID 39684714, 2024). "However, several practical difficulties exist in the clinical application of genetic and analytical methods for detecting CDKN2A mutations in glioma research." (PMID 39457569, 2024). "While the presence of CDKN2A loss is gaining increasing recognition as a key diagnostic and prognostic marker in gliomas and meningiomas, and is an inclusion criterion for some clinical trials, its molecular detection remains expensive, time consuming and not widely available." (PMID 37138345, 2023). "Radiation is the only known environmental risk factor for developing low-grade gliomas, and it increases the risk of homozygous CDKN2A deletion, which is frequently observed in recurrent grade 4 IDHmut astrocytomas and is associated with increased proliferation." (PMID 37932833, 2023). "It has also been shown that in gliomas, hypermutation and acquired CDKN2A deletion are closely associated with an increase in tumor cells at the time of recurrence of this tumor, and that its changes reflect the active growth state in which the tumor cells are in31." (PMID 36967449, 2023). "Notably, expression of IDH1R132H cooperates with platelet-derived growth factor A expression and loss of Cdkn2a, Atrx, and Pten in glioma to mimic the proneural subtype of human GBM, which exhibits a stronger GBM formation ability in vivo." (PMID 36229714, 2023). "Furthermore, radiation increases the risk of de novo glioma tumors with CDKN2A deletions and PDGFRA gains/amplifications." (PMID 37932833, 2023). "Gliomas with CDKN2A mutations are known to have worse prognosis but imaging features of these gliomas are unknown." (PMID 38135704, 2023). "CDKN2A homozygous deletion appears to be associated with poor prognosis in many types of gliomas." (PMID 36900302, 2023). "However, recent studies indicate that CDKN2A-deficient gliomas exhibit heightened lipid peroxidation, leading to selective ferroptosis in the tumor." (PMID 38002949, 2023). "Radiomics displays high accuracy and reliability in predicting CDKN2A/B homozygous deletion, which provides a stepping stone for future clinical applications of molecular genetic diagnostic platforms or AI software in diagnosing gliomas." (PMID 37190513, 2023). "In IDH-mutated gliomas, CDKN2A homozygous deletion is a strong adverse prognostic factor." (PMID 36505786, 2022). "Whether the high-grade gliomas arising in the setting of NF1 occur de novo or from transformation of a pre-existing low-grade glioma following acquisition of additional oncogenic drivers (e.g., CDKN2A deletion, ATRX mutation) remains uncertain." (PMID 35945463, 2022). "In contrast, while 5/6 NF1-associated gliomas epigenetically aligning with IDH-wildtype glioblastoma harbored either CDKN2A homozygous deletion or CDK4 amplification similar to NF1-associated HGAP, only one of these six tumors had ATRX mutation, and none exhibited piloid features." (PMID 35945463, 2022). "Although the biological function of IDH mutation in glioma remains debatable, i.e., oncogenic or tumor-suppressive, the importance of CDKN2A/B homozygous deletion in patient survival may help resolve the controversy." (PMID 35203456, 2022). "The loss of CDKN2A promotes glioma formation and tumor metastasis." (PMID 33959491, 2021). "CDKN2A deletion is associated with the classification and clinical outcomes of glioma." (PMID 33959491, 2021).
glioma (continued). "Cyclin-dependent kinase inhibitor 2A and B (CDKN2A/B) copy number losses (homozygous deletion of CDKN2A-p16INK4α in chromosome 9p) are linked to the activation of the Rb pathway and to the proliferative niches that are observed in gliomas." (PMID 33802571, 2021). "Several studies have detected CDKN2A deletion/loss of p16 protein secretion in high-grade gliomas." (PMID 34745848, 2021). "The deletion of CDKN2A has been associated with poor survival of affected glioma patients." (PMID 32604718, 2020). "For example, those infiltrating gliomas with FGFR-TACC fusions may present with other oncogenic alterations including CDKN2A loss, CDK4 amplification, MDM2 amplification and/or TERT promoter mutations." (PMID 32493417, 2020). "CDKN2A/B loss was found to be significantly enriched in recurrent gliomas." (PMID 31690770, 2019). "Recent studies, however, indicate that additional factors such as loss of CDKN2A or telomerase re-activation may significantly influence the clinical outcome of glioma patients with oncogenic BRAF, suggesting a biological heterogeneity within this subgroup." (PMID 31391125, 2019). "iii)To underline the relevance of investigating and defining if glial tumors with CDKN2A/B and MTAP loss may be vulnerable to new forms of therapy, namely those affecting the methionine salvage pathway." (PMID 30558563, 2018). "The Investigating and defining if glial tumors with CDKN2A/B and MTAP homozygous loss may be vulnerable to new forms of therapy, namely those affecting the methionine salvage pathway, was proven to be of importance." (PMID 30558563, 2018). "Genome-wide association study identifies that CDKN2A was a susceptibility loci for glioma." (PMID 21843312, 2011). "Notably, some histologically low-grade gliomas exhibit aggressive phenotypes due to CDKN2A/B homozygous deletions or H3F3A mutations, while certain high-grade tumors with IDH1/2 mutations may benefit from low-intensity therapies." (PMID 41377022, 2025). "The use of DL in neuropathology, particularly the development of an image-based prediction of molecular driver workflow (e.g., IDH1/2 mutation status or CDKN2A/B copy number status in low-grade gliomas), may provide accessible tools for pathology labs with limited access to molecular testing." (PMID 38893099, 2024). "The most recent grading system of gliomas has integrated the mutation status of key encoding genes prompting a ground-breaking change in the context of glioma diagnosis and treatment with further molecular stratification achieved by determining CDKN2A/B status." (PMID 32631306, 2020). "In mesothelioma and glioma, for instance, concordant loss of p16 and MTAP has been shown to correlate strongly with CDKN2A/B deletion, outperforming either marker alone." (PMID 41596618, 2026). "These gliomas demonstrated a higher prevalence of CDKN2A/B homozygous deletions, an established predictor of poor prognosis in these tumors, and a lower proportion of favorable markers, including IDH mutations and 1p/19q co-deletions." (PMID 40507765, 2025). "The significance of heterozygous deletion of CDKN2A in the prognosis of adult gliomas remains less clear with contradictory results." (PMID 40860828, 2025). "This approach was successfully applied to a panel of breast cancer and glioma cell lines, revealing diverse genetic and epigenetic alterations of CDKN2A." (PMID 40649906, 2025). "Gliomas with ITSS grades 2–3 showed a higher proportion of CDKN2A/B homozygous deletion, which is a well-established predictor of poor prognosis in these tumors." (PMID 40507765, 2025).